IPO5P1 (importin 5 pseudogene 1)
Gene: Transcribed processed pseudogene on chromosome 19 (23,255,148 to 23,255,434, reverse strand). Ensembl gene ENSG00000269837.
Diseases named in the same sentence as IPO5P1 in open-access papers:
IPO5P1 is named in the same sentence as 2 diseases in open-access papers, as found by Europe PMC text mining. Sharing a sentence is not in itself a finding about the gene and the disease. The quoted sentences say what the papers report.
bladder cancer (1 paper, 2022). "A recent study on the prognosis of immune gene-related lncRNAs and immunotherapy suggests that IPO5P1 may be a prognostically important value in bladder cancer patients as well as a predictor of the efficacy of immunotherapy." (PMID 35024796, 2022).
IPO5P1 also shares sentences with these, for which no sentence is quoted: gout (1 paper).